NHP2 (NHP2 ribonucleoprotein)
Description:
Required for ribosome biogenesis and telomere maintenance. Part of the H/ACA small nucleolar ribonucleoprotein (H/ACA snoRNP) complex, which catalyzes pseudouridylation of rRNA. This involves the isomerization of uridine such that the ribose is subsequently attached to C5, instead of the normal N1. Each rRNA can contain up to 100 pseudouridine ('psi') residues, which may serve to stabilize the conformation of rRNAs. May also be required for correct processing or intranuclear trafficking of TERC, the RNA component of the telomerase reverse transcriptase (TERT) holoenzyme.
Synonyms: NOLA2; FLJ20479; DKCB2; NHP2P
Tractability: PROTAC: UniProt records ubiquitination sites on it; ubiquitination databases record sites on it; its protein half-life has been measured.
Gene: Protein-coding gene on chromosome 5 (178,149,459 to 178,153,961, reverse strand). Ensembl gene ENSG00000145912.
Subcellular location: Nucleus, nucleolus; Nucleus, Cajal body
Pathways (Reactome):
Cell Cycle: Telomere Extension By Telomerase
Metabolism of RNA: rRNA modification in the nucleus and cytosol
Gene Ontology:
Molecular function: box H/ACA snoRNA binding; protein binding; RNA binding; telomerase RNA binding; mRNA 3'-UTR binding; U3 snoRNA binding
Biological process: telomerase RNA localization to Cajal body; telomere maintenance via telomerase; rRNA pseudouridine synthesis; snRNA pseudouridine synthesis; snoRNA guided rRNA pseudouridine synthesis
Cellular component: box H/ACA snoRNP complex; box H/ACA telomerase RNP complex; chromosome, telomeric region; telomerase holoenzyme complex; box H/ACA scaRNP complex; nucleoplasm; sno(s)RNA-containing ribonucleoprotein complex; Cajal body; nucleolus; ribonucleoprotein complex
Genetic constraint (gnomAD): Loss-of-function variants: 11 observed, 16.21 expected, observed/expected ratio (o/e) 0.68, 90% interval 0.43 to 1.12. The upper end of that interval is the gene's LOEUF score, 1.12, which puts it in group 4 of 6, group 1 being the genes least tolerant of losing a copy. Missense variants: 179 observed, 203.62 expected, observed/expected ratio (o/e) 0.88, 90% interval 0.78 to 1. Synonymous variants: 86 observed, 82.01 expected, observed/expected ratio (o/e) 1.05, 90% interval 0.88 to 1.25.
Gene-disease validity (ClinGen):
ClinGen rates the evidence that NHP2 causes each of these diseases.
dyskeratosis congenita, autosomal recessive 2 (autosomal recessive): Limited.
Homologues: Orthologues: macaque NHP2 (100% identical), chimpanzee NHP2 (99% identical), guinea pig NHP2 (96% identical), dog NHP2 (95% identical), rabbit NHP2 (95% identical), rat Nhp2 (90% identical), mouse Nhp2 (90% identical), zebrafish nhp2 (71% identical), tropical clawed frog nhp2 (71% identical), Caenorhabditis elegans Y48A6B.3 (44% identical), Drosophila melanogaster NHP2 (42% identical). Paralogues in human: RPL7A (28% identical), RSL1D1 (14% identical), RPL10A (9% identical).
Diseases named in the same sentence as NHP2 in open-access papers:
NHP2 is named in the same sentence as 30 diseases in open-access papers, as found by Europe PMC text mining. Sharing a sentence is not in itself a finding about the gene and the disease. The quoted sentences say what the papers report.
dyskeratosis congenita (10 papers, 2010 to 2021). Dyskeratosis congenita (DC) is a rare ectodermal dysplasia that often presents with the classic triad of nail dysplasia, skin pigmentary changes, and oral leukoplakia associated with a high risk of bone marrow failure (BMF) and cancer. "NHP2 mutations can lead to dyskeratosis congenita, a disease that is clinically characterized by pulmonary fibrosis, cirrhosis, and cancer susceptibility." (PMID 33643914, 2020). "Autosomal forms of Dyskeratosis Congenita can derive from mutations of NOLA2 or NOLA3 encoding for NHP2 and NOP10, respectively." (PMID 29874862, 2018). "Mutations in the Dkc1, Nhp2, and Nop10 genes have been linked to dyskeratosis congenita (DC), a rare but fatal human genetic disorder that impairs stem cell function and proliferation generally attributed to defects in telomerase or ribosome biogenesis." (PMID 25407680, 2014). "Lastly, homozygous or compound heterozygous mutations in the NHP2 gene (nucleolar protein family A, member 2; MIM 606470) have been found in individuals with autosomal recessive dyskeratosis congenita-2 (DKCB2; MIM 613987)." (PMID 24297458, 2014). "For instance, dyskeratosis congenita (DKC), a syndrome characterized by a classic triad of nail dysplasia, skin pigmentary changes, oral leukoplakia, and bone marrow failure, is associated with short telomeres and mutations in TCAB1, dyskerin, NHP2, and NOP10." (PMID 27240403, 2016). "Another genetic disease, known as dyskeratosis congenita (DKC), occurs due to mutations in a couple of genes encoding proteins that localize to CBs (e.g., EST1A, NHP2, NOP10, and WRAP53), and resulting in defective ribosome biogenesis and telomere maintenance." (PMID 32764415, 2020). "Individuals with dyskeratosis congenita (DC), a cancer susceptibility and inherited bone marrow failure syndrome (IBMFS), have mutations in genes important in telomere biology, including DKC1, TERC, TERT, TINF2, NHP2 and NOP10." (PMID 21113082, 2010).
hepatoma (3 papers, 2020 to 2022). "The silencing of the NHP2 gene caused a decrease in of TERT expression, destabilization of the telomerase complex and inhibition of the proliferation of hepatoma cells overexpressing HBx." (PMID 36358677, 2022). "In conclusion, knockdown of NHP2 could inhibit the proliferation of hepatoma cells overexpressing HBx via inhibiting TERT expression." (PMID 33044946, 2020). "HBx was promoted in human hepatoma cell line PLC/PRF5 to simulate HBx-induced HCC, and shRNA-NHP2-1 was subsequently transfected into cells to knockdown NHP2." (PMID 33044946, 2020). "To confirm whether HBx could directly affect TERT and NHP2 expression, we constructed two vectors to overexpress HBx in PLC/PRF5 hepatoma cells." (PMID 33044946, 2020). "In the present study, we knocked down NHP2 expression in PLC/PRF5 hepatoma cell lines with or without HBx overexpression to investigate the regulatory relationship between NHP2 and HBx-induced HCC as well as explore the potential mechanisms." (PMID 33044946, 2020). "Moreover, a component of the telomerase complex, namely NHP2, has been found overexpressed along with TERT enzyme in HBV-related HCC as well as in HBx-transduced hepatoma cell lines." (PMID 36358677, 2022). "The knockdown of NHP2 also suppressed HBx-transduced hepatoma cell growth in a xenograft animal model, suggesting that therapeutic approaches targeting NHP2 may provide a novel strategy for treating HBV-related HCC." (PMID 36358677, 2022).
pulmonary fibrosis (3 papers, 2020 to 2025). Chronic progressive interstitial lung disorder characterized by the replacement of the lung tissue by connective tissue, leading to progressive dyspnea, respiratory failure, or right heart failure. "Notably, the father of the index case, who has pulmonary fibrosis, does not carry the NHP2 variant." (PMID 40134350, 2025).
bone marrow failure (2 papers, 2020 to 2023). "Here, we report two novel NHP2 variants (NHP2-A39T and NHP2-T44M) identified in a compound heterozygous patient affected by premature aging, bone marrow failure/myelodysplastic syndrome and gastric cancer." (PMID 37440454, 2023).
colorectal cancer (2 papers, 2019 to 2022). A primary or metastatic malignant neoplasm that affects the colon or rectum. "NHP2 and its encoding gene have been shown to be overexpressed in gastric and colorectal cancers." (PMID 35054812, 2022).
cyst (2 papers, 2021 to 2024). A sac-like closed membranous structure that may be empty or contain fluid or amorphous material. "What is more, the downregulation of NHP2, derived from one H/ACA box RNP catalyzing rRNA pseudouridylation, could result in cyst formation." (PMID 34195281, 2021).
endometrial cancer (1 paper, 2023). Primary or metastatic malignant neoplasm involving the endometrium (mucous membrane that lines the endometrial cavity). "Interestingly, it has been shown that NHP2 expression level was associated with prognosis in endometrial cancer." (PMID 36370117, 2023). "Altogether, NHP2 mRNA levels was not only associated with poor outcome in endometrial cancer independently of the specific therapy in large cohort but also high mRNA levels of NHP2 in diagnostic biopsies distinguish non‐responders from responders to Vistusertib + Anastrozole combination treatment." (PMID 36370117, 2023).
familial breast cancer (1 paper, 2021). "NHP2 ribonucleoprotein (NHP2, also termed DKCB2, NHP2P, and NOLA2) is a telomere-related gene, and changes in its coding sequence may be involved in the pathogenesis of familial breast cancer." (PMID 34193202, 2021).
lung adenocarcinoma (1 paper, 2023). A carcinoma that arises from the lung and is characterized by the presence of malignant glandular epithelial cells. "Furthermore, low expression levels of the other RNP core protein components NHP2, NOP10, and GAR1 were also associated with poor prognosis levels in lung SCC and ovarian cancer, but not in lung adenocarcinoma or HNSCC." (PMID 36732018, 2023).
lung carcinoma (1 paper, 2021). "But, NHP2 was weakly expressed in lung cancer samples, when compared to paired normal lung tissue." (PMID 33288886, 2021).
Pancytopenia (1 paper, 2023). An abnormal reduction in numbers of all blood cell types (red blood cells, white blood cells, and platelets). "We herein report two novel variants in the NHP2 gene (OMIM #613987), NHP2-A39T and NHP2-T44M, identified in a patient diagnosed with pancytopenia and signs of early aging." (PMID 37440454, 2023).
uterine corpus endometrial carcinoma (1 paper, 2023). A endometrial carcinoma (disease) that involves the body of uterus. "Using a series of 543 uterine corpus endometrial carcinoma (UCEC) issued from the TCGA database, a significant association was observed for NHP2 (P = 0.0003) and TAF1B (P = 0.034), but not for Nop10 (P = 0.77), − high levels of NHP2 and TAF1B being associated with the poorest outcome." (PMID 36370117, 2023).
cancer (8 papers, 2020 to 2025). A tumor composed of atypical neoplastic, often pleomorphic cells that invade other tissues. "Survival analysis implies NHP2 protein levels may also carry prognostic significance in cancer associated survival, with improved survival in EC with high abundance of NHP2." (PMID 35054812, 2022). "In this study, we report a statistically significant negative association between NHP2 and cell proliferation marker Ki67, indicating NHP2 loss may occur due to sustained cell proliferation signalling, one of the hallmarks of cancer." (PMID 35054812, 2022). "Differential expression and pathway enrichment analyses revealed that NOP10- and NHP2-positive PTCs are enriched in pathways critical to cancer biology, including DNA repair, mTORC1 signaling, oxidative phosphorylation, hypoxia, and ROS response." (PMID 41357133, 2025). "Because NHP2 is essential, MYC-tagged wild-type NHP2 (NHP2-WT) or mutant NHP2 (NHP2-A39T or NHP2-T44M) were expressed in telomerase-positive HeLa cancer cell line first, and then the bulk endogenous NHP2 was targeted with CRISPR/Cas9." (PMID 37440454, 2023). "Similar data were obtained with the cancer cell line HT1080, validating both NHP2-A39T and NHP2-T44M as new TBD-causing NHP2 variants." (PMID 37440454, 2023). "Previous studies have explored the expression and clinical significance of NHP2 in various cancer types." (PMID 35054812, 2022). "Importantly, similar competition between endo-NHP2 and exogenous NHP2 and the instability of NHP2-A39T and NHP2-T44M was also observed in U-2OS, HeLa cancer cells and in normal BJ fibroblasts." (PMID 37440454, 2023). "NHP2 depletion has been previously shown to affect DNA damage response in cancer cells." (PMID 37440454, 2023). "DKC1, RUVBL1, NHP2, and TERC expression was also inversely correlated with DNA methylation in most cancer types." (PMID 36239411, 2023). "These genes have varying supporting functions expected from a cancer cell population, including, for example, supporting cell proliferation (NPM1) and telomere maintenance (NHP2)." (PMID 36598637, 2023). "Recently, the aberrant expression pattern of DKC1, NHP2, and NOP10 in several cancer entities has been reviewed." (PMID 33803145, 2021).
tumor (6 papers, 2017 to 2025). "scRNA-seq revealed that proximal tubule cells (PTCs) with telomerase-associated genes NOP10 and NHP2 exhibited complex senescence dynamics, characterizing distinct cellular communication patterns in the tumor microenvironment." (PMID 41357133, 2025). "Specifically, we reveal how PTCs with telomerase-associated genes, like NOP10 and NHP2 dynamically modulate cellular senescence and interact with the tumor microenvironment." (PMID 41357133, 2025). "The global communication networks further highlight strong interaction strengths between NOP10+/NHP2+ PTCs and these microenvironmental cell types, reinforcing the notion that these populations are actively engaged in shaping the tumor milieu." (PMID 41357133, 2025). "Experimental evidence demonstrated age-associated NHP2 overexpression in CRC pathological specimens, while subsequent in vitro and in vivo models confirmed its pivotal role in tumor progression through telomere homeostasis modulation, thereby mediating critical oncogenic biological processes." (PMID 41394399, 2025). "The MIF pathway, in particular, has been implicated in tumor inflammation and immune evasion, and its activation in NOP10+/NHP2+ PTCs may facilitate cross-talk with macrophages and T cells, contributing to an immunosuppressive niche in the ccRCC TME." (PMID 41357133, 2025). "Besides TERT, other genes encoding telomerase holoenzyme complex proteins such as DKC1 (Xq28), which we identified significantly upregulated in clinically aggressive tumours, and NHP2(5q35), are within the 5‐Mb‐ends of their respective chromosomes." (PMID 35979662, 2022). "Pie chart analysis illustrated a progressive reduction in the proportion of NHP2- and NOP10-positive tumor cells across cell states, supporting these mechanistic insights, and overall ratios were similar between the two markers." (PMID 41357133, 2025). "NHP2 expression mirrored the rise and fall of senescence scores along pseudotime, while NOP10 was consistently downregulated in tumor cells, implying its potential role in senescence escape." (PMID 41357133, 2025). "During tumor evolution, telomerase reactivation—possibly modulated by NOP10 and NHP2—enables cells to evade senescence and acquire malignant traits." (PMID 41357133, 2025).
NHP2 also shares sentences with these, for which no sentence is quoted: colonic cancer (2 papers); cardiac hypertrophy (1); Cirrhosis (1); Dubowitz syndrome (1); gastric cancer (1); genetic disorder (1); idiopathic pulmonary fibrosis (1); lymphoma (1); monoclonal gammopathy of undetermined significance (1); myelodysplastic syndrome (1); myeloma (1); neuroblastoma (1); ovarian carcinoma (1); plasma cell disorders (1); plasma cell leukemia (1); squamous cell lung carcinoma (1).